MMP9 (matrix metallopeptidase 9)
Diseases named in the same sentence as MMP9 in open-access papers (continued):
Sharing a sentence is not in itself a finding about the gene and the disease.
colitis (continued). "In the present study, we examined the anti-inflammatory effect of procyanidin in dextran sulfate sodium (DSS)-induced colitis and found that procyanidin decreased the generation of ROS, inhibiting the expression of MMP9, NF-κB, and formation of the NLRP3 inflammasome." (PMID 29354126, 2017). "The DAI was lower in MMP-9−/− mice with chronic DSS colitis compared to WT mice." (PMID 28561062, 2017). "We have shown that epithelial cell-derived MMP9 mediates tissue damage during colitis." (PMID 27861153, 2017). "We have shown that MMP9 is protective in CAC contrary to its inflammatory role in acute-colitis." (PMID 27861153, 2017). "Thus, OMV-linked factors other than TcpC should contribute to the modulation of mucosal healing markers like TFF-3 and MMP-9, observed in this experimental murine colitis model." (PMID 28744268, 2017). "Moreover, our in vivo data showed that procyanidin attenuated Dextran sulfate sodium-induced experimental colitis in a dose-dependent fashion by suppressing the expression of MMP9, NF-κB, and NLRP3 inflammasome signaling in colonic tissues in mice." (PMID 29354126, 2017). "This anti-fibrotic effect, associated with the anti-inflammatory effect of MMP-9 inhibitor described in the DSS-colitis model by Marshall and colleagues using an alternative anti-MMP-9 antibody, AB-004631, supports the development of an anti-MMP-9 antibody in patients with penetrating CD." (PMID 29247242, 2017). "In conclusion, we did not observe a causal role of MMP-9 in three different models of colitis: two acute inflammatory models and one chronic fibrostenosing model." (PMID 28561062, 2017). "Our findings and the available literature reports suggest that MMP-9 plays an important role in the pathogenesis of colitis and may be a potential target for anti-inflammatory therapy." (PMID 27034654, 2016). "It is interesting to note that while colitis is mediated by MMP-9, the same enzyme may play a protective role in CAC." (PMID 25948887, 2015). "Chymase has been shown to be a relevant activator of pro-MMP-9 in DSS induced colitis." (PMID 25948887, 2015). "Therapeutic dosing of AB0046 in a DSS-induced colitis model of UC showed that inhibiting MMP9 after disease was established significantly improved multiple disease parameters, including histopathology and the clinically relevant metrics of body weight loss, diarrhea, and endoscopic disease." (PMID 25961845, 2015). "Moreover, MMP-9-null mice exposed to DSS or to S. Typhimurium were previously significantly protected from colitis, confirming MMP-9's importance in the etiology of the disease." (PMID 24465207, 2014). "Therefore, although MMP-9 mediates pro-inflammatory responses in colitis, it has a protective role and acts as a tumor suppressor in CAC." (PMID 24518611, 2014). "Furthermore, increased secretion of Lcn2 stabilized MMP-9 via direct protein-protein interaction, which further aggravated the colitis." (PMID 24465207, 2014). "Since activated macrophages are known to aggravate the colitis symptoms by inducing the MMP-9 expression, we checked whether GSC extract affected MMP-9 mRNA expression in LPS-induced RAW264.7 cells." (PMID 23841050, 2013). "MMP-9 is proposed to play an important role in experimental colitis." (PMID 21151942, 2010). "Finally, the combination of Homo and MMP9 inhibitors was utilized to verify whether Homo alleviates DSS-mediated colitis in mice through modulation of MMP9." (PMID 40529132, 2025).
colitis (continued). "It was also found that the elevated MMP3 and MMP9 induced by serotonine might be associated with the serotonine-exacerbated DSS-induced colitis of mice, and the increased circulating MMP3 and MMP9 had been considered as biomarkers of the clinical activity of IBD." (PMID 35493520, 2022). "Therefore, we decided to check whether serum MMP-9 may distinguish children with right-sided (E3, E4) colitis from those with left-sided (E1, E2) colitis." (PMID 35566780, 2022). "Importantly, a humanized MMP9 antibody (andecaliximab) has reached advanced clinical trials for the treatment of colitis (ClinicalTrials.gov: NCT02405442) and alimentary tract cancer (ClinicalTrials.gov: NCT01803282); hence, it may also be repurposed for CIPN." (PMID 32347537, 2020). "In the present study, we found that MMP9 could be secreted by macrophages, which accounted for most of the inflammatory response during colitis and we found, for the first time, that procyanidin could downregulate the high MMP9 expression induced by LPS stimulation in THP-1 cells." (PMID 29354126, 2017). "In addition, it has been also shown that infliximab, an anti-TNF-alpha antibody, could prevent CAC in DSS-induced colitis, an effect which was accompanied by the reduction of MMP-9 and MMP-11 levels." (PMID 25948887, 2015). "This novel mechanism by which S. Typhimurium exploits the host Lcn2 and MMP-9 synergy to aggravate inflammation and colitis severity is critical, as it calls for the reinterpretation of studies on microbial pathogenesis; other potential pathogens may also employ similar mechanisms." (PMID 24465207, 2014). "Post-colitis (therapeutic) EP administration produced greater suppression of MMP-2, MMP-9, NF-κB, HMGB1 and iNOS, along with superior restoration of TAC (P < 0.05), indicating timing-dependent modulation of inflammatory and matrix degradation pathways." (PMID 42307112, 2026). "At the level of mRNA, the relative expression of TNFα, IL1β, IL6, MMP9, and PTGS2 increased significantly in DSS-induced colitis compared with the control group." (PMID 39064786, 2024). "MMP-9 was identified as an important marker of inflammation in both UC and CD, and targeting MMP-9 in preclinical models has led to attenuated colitis." (PMID 39771552, 2024). "AAV-mediated inhibition of Mmp9 significantly ameliorated DSS-induced clinical and pathological manifestations of colitis in the Olfm4-/- mice." (PMID 37151883, 2023). "To identify factors involved in the accumulation of Aβ released from these neutrophils, we administered DNase, an inhibitor of NETs, MMP-9 inhibitor, or N-acetyl-l-cysteine (NAC, an inhibitor of ROS), to mice with DSS-induced colitis." (PMID 36922861, 2023). "MMP-2 and MMP-9 levels were consistently up-regulated during active flare-ups of IBD in patients and an animal colitis model." (PMID 36289761, 2022). "In rats with TNBS-induced colitis, MPO activity got its maximum on days 7 and 10 post-induction and was consistent with the up-regulation of MMP-9 in peripheral and colonic neutrophils which modulates transmural colonic damage." (PMID 35766160, 2022). "Upregulation of several secreted MMPs has been reported in the colonic mucosa of dogs with colitis, including MMP-1, MMP-3, and MMP-13, as well as MMP-2 and MMP-9." (PMID 35751094, 2022). "Most MMPs, such as MMP-2, MMP-3, MMP-7, MMP-9, MMP-10, MMP-12, and MMP-13 are increased in colitis and CAC." (PMID 36776395, 2022). "It was also effective against TNBS-induced colitis in a dose dependent-manner, reducing DAI scores by more than 50% and concomitantly inhibiting MMP-9 activity." (PMID 35631241, 2022). "The overexpression of inflammatory-related proteins, MMP-2, MMP-9 and MMP-13 has been reported to be involved in colon damage during colitis." (PMID 35159480, 2022).
colitis (continued). "Transgenic mice over-expressing MMP9 had defective barrier function, altered mucin secretion and increased IL-8, and exhibited worsening of acute colitis in DSS or Salmonella-induced colitis models." (PMID 35620197, 2022). "WB and immunofluorescence experiments confirmed that the expression levels of MMP-9, PTGDS, SLC26A8, and CD160 in colitis were significantly increased, whereas that of TLR5 were decreased." (PMID 36733384, 2022). "The expression of MMP-9, PTGDS, SLC26A8, and CD160 in colitis was increased in the IBD mouse model, whereas the expression of TLR5 was downregulated." (PMID 36733384, 2022). "The pharmacological evaluation showed that FMPs attenuated inflammation in AA-induced colitis by reducing the serum concentrations of TNF-α, IL-6, IL-8, and IL-10 and the colonic concentrations of MPO, MMP9, and CXCR1." (PMID 35620404, 2022). "The elevation in the colonic contents of MPO, MMP-9, and MCP-1 was intensified in mice exposed to acrylamide as compared with the control colitis mice." (PMID 33995942, 2021). "Experimental colitis increased the activity of MPO and the levels of MCP-1 and MMP-9 as markers of inflammatory damage in the colonic tissue." (PMID 33995942, 2021). "In the present study we showed that colitis induction significantly increased MPO, MCP-1, and MMP-9 levels in the colon tissue." (PMID 33995942, 2021). "Induction of colitis in mice pretreated with acrylamide resulted in an additional elevation in colonic MPO, MCP-1, and MMP-9 levels." (PMID 33995942, 2021). "CGS-27023-A (MMI-270), a sulfonamide derivative that has a broad spectrum of inhibition for MMPs, has been shown to attenuate colonic mucosal injury in TNBS-induced colitis in rats by reducing MMP-2 and MMP-9 expression." (PMID 33802197, 2021). "We have also reported the alleviated mucosal and neuronal damage in recurrent colitis and the development of intestinal strictures due to high MMP9 (matrix metallopeptidase-9) and lower TIMP1 (TIMP metallopeptidase inhibitor 1) expression in the colon." (PMID 31010141, 2019). "In mice, mangiferin, a bioactive compound of the mango, attenuated DSS induced colitis through directly reducing the activity of mucosal TNF-α and MMP-9." (PMID 29530095, 2018). "In this study, we investigated changes in microbiota in co-housed WT and MMP-9-/- mice in control and acute DSS-induced colitis conditions." (PMID 30181895, 2018). "Pathogenic angiogenesis and elevated levels of both VEGF and MMP-9 were demonstrated in different models of UC, including a DSS-induced colitis model." (PMID 30619283, 2018). "It has been demonstrated that 5-HT exacerbated DSS-induced colitis by upregulating MMP-3 and MMP-9 expression in mice." (PMID 28694565, 2017). "We find similar colonic gene expression profiles in wild type and MMP-9 knockout mice in control and acute DSS conditions with the exception of eleven genes involved in antimicrobial response during colitis." (PMID 28561062, 2017). "In DSS colitis in mice, targeted deletion of MMP-9 has a protective effect, whereas mice overexpressing MMP-9 develop more severe colitis." (PMID 28736729, 2017). "After induction of acute colitis with DSS, the relative body weight curves of WT and MMP-9−/− mice changed similarly." (PMID 28561062, 2017). "ROS at high levels can induce many harmful responses, and serve as a common upstream of many inflammatory signaling, such as MMP9, NF-κB, and NLRP3 inflammasome pathway, which contribute much to the initiation and progression of colitis." (PMID 29354126, 2017). "5-HT exacerbated DSS-induced colitis, low-dose 5-HT induces both MMP-3 and MMP-9, and high-dose 5-HT only increased MMP-3 mRNA expression in mouse colon." (PMID 27478308, 2016). "Our results support the notion that 5-HT exacerbates DSS-induced colitis by enhancing the production of MMP-3 and MMP-9." (PMID 27478308, 2016).
colitis (continued). "In contrast, strong MMP9 expression was evident at disease foci in UC and in DSS-colitis tissue, including in abscessed and necrotic crypts and regions of cryptitis, as well as in the lamina propria." (PMID 25961845, 2015). "In this context, the increasing levels of MMP-9 lead to an increased endostatin concentration and treatment with endostatin in MMP-9−/− mice can reduce the severity of colitis indicating a protective role for the enzyme." (PMID 25948887, 2015). "Transgenic mice overexpressing epithelial MMP-9 developed worse DSS and ST induced colitis which correlated with an increased expression of KC." (PMID 25948887, 2015). "VPAC1, a receptor for vasoactive intestinal peptide (VIP), enhances DSS induced colitis through activation of PKA and increased MMP-9 expression, among other mediators." (PMID 25948887, 2015). "Likewise, IBD-related inflammation is associated with increased expression of MMPs, and studies in DSS model of colitis specifically reported exaggerated expression of MMP-3 and MMP-9." (PMID 40839695, 2025). "Screening of disease markers for colitis in mice using a machine-learning approach revealed that the expression levels of SLC26A8, MMP9, PTGDS, and CD160 were significantly elevated in colitis tissues, whereas the expression level of TLR5 was significantly reduced." (PMID 40110435, 2025). "Finally, the expression of the revealed hub genes related to acute colitis (C3, Tyrobp, Mmp3, Mmp9, Timp1) and CAC (Timp1, Adam8, Mmp7, Mmp13) was validated by qRT-PCR in the colon tissue of mice with acute colitis and colitis-driven adenomas." (PMID 36901742, 2023). "Despite the extensive studies of MMPs as candidate marker genes of colitis and CAC, to the best of our knowledge, the complex evaluation of the expression of Mmp3, Mmp7, Mmp9, and Mmp13 in acutely inflamed, adenomatous, and adjacent colon tissues has not yet been reported." (PMID 36901742, 2023). "The real conclusion came with the demonstration, against prevailing literature, that genetic deletion of MMP-9 or inhibition of MMP activity are not protective against experimental colitis in mouse models." (PMID 36164340, 2022). "The present study aimed to evaluate the nutrient and antioxidant value of the LPC, to test its efficacy as a food additive for wheat cookies in reducing colitis in vivo, using two different models of IBD, and in inhibiting MMP-9 and other inflammatory pathways, including oxidative stress." (PMID 35631241, 2022). "Other studies in the intestinal tissue from IBD patients and mice with dextran sodium sulfate-induced colitis have shown that macrophages are the main source of MMP-8, MMP-9 and MMP-10 during IBD, which suggests a significant role of neutrophils in intestinal tissue infiltration." (PMID 33800267, 2021). "Recently, we showed that MMP-9 induced increase in intestinal epithelial TJ permeability was also mediated by an increase in MLCK expression in a p38 kinase-dependent manner in vitro and in vivo and in a DSS-colitis mouse model." (PMID 33826658, 2021). "Despite its central importance in mediating the inflammatory process in IBD and animal models of colitis, the intracellular mechanisms of MMP-9 regulation of intestinal TJ barrier function have not been identified." (PMID 33826658, 2021). "A previous study highlighted the protective effects of intraperitoneally administered pentoxifylline—a xanthine alkaloid derived from the seeds of the cacao tree (Theobroma cacao)—on TNBS colitis in rats through limiting TGFβ1 accumulation and MMP3 and MMP9 activation." (PMID 32855621, 2020). "Matrix metalloproteinase-9 (MMP-9), whose function is to breakdown extracellular matrix proteins in inflammatory environments, is upregulated during IBD and is an essential mediator of tissue injury during DSS colitis." (PMID 31811125, 2019). "In contrast to published data, we did not observe protective effects by MMP-9 gene deletion on colitis phenotypic scores." (PMID 30181895, 2018).
colitis (continued). "On the other hand, Mmp9 and Cnlp were upregulated in HSD mice after DSS-colitis." (PMID 29566748, 2018). "Consistent with in vitro data, procyanidin significantly downregulated MMP9, NF-κB, and NLRP3 inflammasome signaling pathway in DSS-induced colitis in mice, which might due in part to the decreased number of macrophages." (PMID 29354126, 2017). "In experimental studies, the dextran sulfate sodium- (DSS-) induced colitis has shown a lack of MMP-9 expression in healthy intestinal mucosa which is upregulated in inflamed mucosa of IBD." (PMID 27034654, 2016). "Studies in animal models have confirmed that the lack of MMP-9 −/− expression in the DSS-induced colitis determines a reduction in inflammation and damage to the intestinal mucosa." (PMID 27034654, 2016). "5-HT induced MMP-3 and MMP-9 expression in mouse colon; these elevated MMPs may contribute to DSS-induced colitis." (PMID 27478308, 2016). "In certain instances, NO and peroxynitrite can modulate MMP-9 expression and activity and it is likely that the antioxidant properties of melatonin could reduce colon gelatinase expression in DNBS induced colitis." (PMID 25948887, 2015). "It has also been shown that infliximab could reduce the incidence of tumour development through reduction of MMP-9 and -11 in DSS-induced colitis." (PMID 25948887, 2015). "Heimesaat and colleagues demonstrated that MMP2 and MMP9 are involved in DSS-induced colitis but while MMP2 is crucial in the pathogenesis of colitis, MMP9 seems not to be essential." (PMID 25890182, 2015). "While rodent DSS-induced colitis does not model the autoimmune etiology of UC, it is a robust model for the role of MMP9 in colitis." (PMID 25961845, 2015). "Compared with the TNBS model group, the DAI scoring, plasma and colonic mucosa Hcy levels, MPO activity and contents of MDA, IL-1β, IL-6, TNF-α, MMP-2, MMP-9 in colon and EB in small intestine were significantly increased in the TNBS-induced colitis rats with simultaneous Hcy injection (P < 0.01)." (PMID 24787389, 2014). "Pharmacological inhibition of MMP-9 with bioactive peptides does not improve DSS-induced colitis, suggesting that the upregulation of MMP-9 may be a consequence of intestinal inflammation rather than a cause." (PMID 39712025, 2024). "Additional studies using in vivo models of colitis and CAC found that the expression signature of colitis (i.e., Mmp3 and Mmp9) versus that of CAC (i.e., Mmp7 and Mmp13) could predict the development of CAC in mice with dextran sulfate sodium (DSS)-induced colitis." (PMID 38288108, 2023). "In line with the results of network pharmacology approach, in vivo studies confirmed that FC alleviated DSS-induced colitis, reduced systemic inflammatory response, and diminished the expression of IL-17 signaling pathway mediators, IL-17A, RORγt, and tissue remodeling factors MMP1, MMP3 and MMP9." (PMID 37161415, 2023). "A 16-gene signature (CARD12, CCL3, CCR3, CXCL1, F5, FAM210B, GADD45A, IL18bp, IL2RA, IL5, IL8, MMP9, PTGS2, SOCS3, TLR9 and UBE2C) was identified from 30 days post-tremelimumab initiation blood that discriminated patients developing grade 0–1 from grade 2–4 diarrhea/colitis." (PMID 30227886, 2018). "After induction of acute colitis with DSS, we found with EdgeR and CuffDiff2 analyses that the expression of 11 genes (Clps, Ddx60, Fgb, Fgg, Ifi44, Ifit2, Isg15, Itih3, Itih4, Oas3 and Usp18), which are involved in antimicrobial response, was increased in MMP-9−/− compared to WT mice." (PMID 28561062, 2017). "However the precise role of MMP9 has never been studied in the setting of chronic colonic inflammation/CAC." (PMID 27861153, 2017). "Pharmacological inhibition of MMP-9 with bio-active peptides does not improve DSS colitis." (PMID 28561062, 2017). "Indeed, it has been demonstrated that epithelial and not neutrophil-derived MMP-9 mediates tissue damage during colitis." (PMID 27999328, 2016).